LEP (leptin)
Diseases named in the same sentence as LEP in open-access papers (continued):
Sharing a sentence is not in itself a finding about the gene and the disease.
Obesity (continued). "High BMI and obesity are associated with higher circulating levels of CGRP, substance P and leptin, but reduced concentrations of adiponectin, which in turn may be linked to a pro-inflammatory state subsequent to the excessive production of proteins such as TNF-α." (PMID 38347465, 2024). "Furthermore, obesity and its consequences can lead to an imbalanced adipokine profile, increasing levels of proinflammatory adipokines and cytokines including retinol-binding protein 4, lipocalin 2, Leptin, and chemerin." (PMID 38898498, 2024). "The findings propose that therapeutic strategies targeting these adipokine pathways, particularly modulating leptin and boosting adiponectin, could potentially improve cardiac function and exercise tolerance in individuals suffering from obesity-related cardiovascular dysfunction." (PMID 39682585, 2024). "Although the decrease in TET2 expression in adipocytes did not prevent the increase in leptin levels during obesity, the loss of Tet2 in obese mice resulted in the downregulation of leptin levels and an enhancement of leptin sensitivity, which ultimately led to weight loss." (PMID 38561362, 2024). "Complete absence of leptin or its inability to signal, caused by loss-of-function mutations of the ligand or its receptor in both rodents and humans, respectively, produces profound obesity." (PMID 38165042, 2024). "However, in pathological situations such as obesity and hyperglycemia, considerably high levels of leptin have been found, which might be due to leptin resistance." (PMID 38234664, 2024). "Additionally, early exposure to obesity or overfeeding may raise leptin levels during early development, potentially changing the relationship between the hypothalamus and SNS." (PMID 39963180, 2024). "Furthermore, studies demonstrated that elevated levels of leptin in children with obesity may precipitate early onset of puberty." (PMID 40302954, 2024). "Mice with elevated GPx-1 expression exhibit a T2D-like phenotype characterized by obesity, hyperglycemia, hyperlipidemia, hyperinsulinemia, insulin resistance, increased pancreatic β-cell mass, glucose-stimulated insulin secretion, elevated plasma leptin levels, and hepatic lipogenesis." (PMID 39469571, 2024). "Therefore, elevated leptin levels may contribute to obesity and insulin resistance as a consequence of this, in a positive feedback loop, may promote the development of metabolic disorders." (PMID 39684379, 2024). "Obesity may also impair the immune system by contributing to leptin resistance." (PMID 39163102, 2024). "Leptin, which rises in direct correlation with obesity, promotes proinflammatory responses by activating immune cells and enhancing cytokine production, while adiponectin, which has decreasing levels with obesity, has anti-inflammatory properties and may reduce airway hyperreactivity." (PMID 40474934, 2024). "The clinical characteristics of extreme obesity, decreased satiety, intense hyperphagia, persistent food-seeking behavior, recurrent bacterial infections, hyperinsulinemia, liver steatosis, dyslipidemia, and hypogonadotropic hypogonadism are the outcomes of a complete leptin deficit." (PMID 39125635, 2024). "Conceivably, partial leptin inhibition could restore leptin sensitivity and reduce obesity." (PMID 38186879, 2024). "Additionally, studies on mice have shown that the activation of c-Jun N-terminal kinase 1 (JNK1) and inhibitor of nuclear factor kappa-B kinase 2 (IKK2) plays a key role in the development of insulin and leptin resistance in AgRP neurons and, therefore, increased appetite and obesity development." (PMID 39125772, 2024). "Thus, increased leptin concentrations are correlated with decreased body weight, but elevated levels of leptin can be found with increased body fat levels seen in patients with obesity, suggesting an endogenous resistance to leptin." (PMID 39776746, 2024).
Obesity (continued). "In addition to the association with increased vessel caliber resulting from the need to adapt to the adverse environment, factors that are elevated in obesity, such as leptin, induce the proliferation of VSM cells, using the nuclear factor kappa B (NF-kB) and kinase pathways." (PMID 39758349, 2024). "An increase in irisin concentrations in an obese state for a long period is a pathological condition and might be an adaptive compensatory response to hyperglycemia, although it finally results in potential irisin resistance, such as insulin and leptin resistance, which occurs in obesity." (PMID 39479712, 2024). "Therefore, increasing the leptin level is considered as a target for the treatment of obesity." (PMID 39590824, 2024). "Therefore, hyperleptinemia in obesity may act as a compensatory mechanism to overcome leptin resistance." (PMID 38397015, 2024). "Obesity is a chronic inflammatory disorder, associated with adipocyte hypertrophy and secretion of pro-inflammatory cytokines, such as interleukin (IL)-6, IL-1, IL-8, and tumor necrosis factor (TNF)-α, as well as adipokines such as leptin, adipsin, resistin, and visfatin by adipose tissue." (PMID 38864906, 2024). "Furthermore, obesity, through leptin signaling, contributes to the growth and metastasis of BC by supporting immunosenescence but, paradoxically, T cell senescence resulting in an increase in PD-1 expression and dysfunction can better predispose obese subjects to checkpoint blockade therapy." (PMID 38892411, 2024). "Moreover, leptin may be a biomarker connecting adiposity, obesity, and OA in terms of aging and serve to monitor the severity of the disease." (PMID 39229323, 2024). "However, in obesity, resistance to both insulin and leptin can develop, impacting uterine function." (PMID 39767708, 2024). "Consequently, the significant reductions in PBMC gene expressions of IL-6, IL-1β, and leptin, marked by their comparatively large effect sizes, collectively point toward a potential state of controlled inflammation in the realm of obesity subsequent to NS oil supplementation." (PMID 38178093, 2024). "Additionally, certain leptin gene SNPs increased CRC susceptibility in females regardless of obesity, whereas a specific ADIPOQ SNP manifested only in obese males, suggesting gender-specific CRC predispositions." (PMID 38904048, 2024). "In HFD-induced obese mice, the level of leptin increased, and the level of adiponectin decreased; the administration of YC-1102 decreased leptin levels and increased adiponectin levels in a dose-dependent manner, implying an ameliorating effect of YC-1102 on obesity and its related symptoms." (PMID 38392211, 2024). "However, multiple studies indicate HFD-induced obesity impairs leptin transport across the BBB." (PMID 38678254, 2024). "This might be due to the correction of leptin resistance, which is increased in obesity." (PMID 38673991, 2024). "Moreover, poorly regulated concentrations of insulin, IGF, inflammatory cytokines, and hormones like leptin and estrogen in individuals with diabetes and obesity disrupt the DNA helix and refashion the DNA damage response mechanism, causing genomic instability, a hallmark of cancer." (PMID 39692821, 2024). "Leptin resistance, which refers to the brain areas such as the hypothalamus and hindbrain being unable to respond to plasma leptin levels, could potentially contribute to the onset of obesity." (PMID 39335642, 2024). "Interestingly, in the treatment of obesity and leptin resistance, or precisely its consequences, the endocannabinoid system may be helpful." (PMID 39057043, 2024). "Itaconate may be a link between leptin, obesity, and colorectal cancer development." (PMID 39621160, 2024). "Hence, it is plausible that leptin may have a role in the development of hemostatic disorders in MASLD also due to its connections with obesity, a condition frequently characterized by dysregulation of leptin." (PMID 38255708, 2024).
Obesity (continued). "Moreover, since the upregulation of ITGB3 is provoked by a low concentration of leptin, this may potentially indicate that obesity, characterized by elevated levels of this hormone, may negatively affect uterine receptivity." (PMID 38999965, 2024). "Furthermore, certain factors associated with obesity, such as insulin resistance and plasma leptin levels, were not measured in this study." (PMID 38553569, 2024). "Therefore, a triangular relationship exists between leptin, obesity, and CRC." (PMID 39201522, 2024). "Additionally, in the present study, when leptin levels were compared in individuals with obesity, they showed higher leptin levels (point estimate 1.09, lower-upper range: 0.82–1.35) than individuals with diabetes (point estimate 0.55, lower-upper intervals: 0.34–0.77)." (PMID 39684379, 2024). "This suggests that increased leptin may serve as a linking condition between obesity and OSA." (PMID 38915794, 2024). "Indeed, there is the potential that elevated leptin concentrations in individuals with overweight and obesity during infectious cycles (e.g., seasonal flu) may potentiate hyper-inflammatory T-lymphocyte responses, and their chronic activation." (PMID 38538853, 2024). "Additionally, obesity may lead to increased leptin and decreased adiponectin release from adipose tissue, potentially increasing osteoclast activity and resulting in bone loss." (PMID 38890674, 2024). "Similarly, only a single study investigated the effectiveness of carnosine supplementation on other adipokines, including serum leptin, resistin, and adipsin, indicating that carnosine intake reduced serum leptin and resistin levels in adults with overweight or obesity." (PMID 38086332, 2024). "This suggests that obesity caused by caponization is closely related to LEP resistance, similar to a previous finding that exogenously administered LEP did not induce a signal transducer and activator of transcription 3 (STAT3) phosphorylation and or increase SOCS3." (PMID 39201373, 2024). "Unexpectedly, the increased leptin concentrations were not always associated with obesity." (PMID 39544232, 2024). "Therefore, in this narrative review, we will discuss the evidence linking leptin with the presence, severity, and/or prognosis of obesity and T2DM regarding CV disease, aiming to shed light on the potential implications for better management and preventive strategies." (PMID 38397015, 2024). "Higher leptin concentrations, while not directly associated with obesity, may have a role in the perception of pain among women." (PMID 38792501, 2024). "Given the profound impact of BMI on leptin levels and the prominent role of obesity in endometrial cancer, leptin may not be an ideal candidate as a diagnostic or prognostic marker for this cancer." (PMID 38339282, 2024). "Despite the fact that leptin inhibits appetite, obese individuals have higher serum leptin levels and may be leptin resistant, which is comparable to the insulin resistance that is frequently observed in obesity." (PMID 38828407, 2024). "Another possible mechanism by which leptin could stimulate the hypertrophy program is through the activation of the fat mass and obesity-associated (FTO) gene, which has been shown to be closely related to obesity in experimental animals." (PMID 38256208, 2024). "The hippocampus also has receptors for leptin, and leptin resistance could alter the synaptic plasticity of this structure, making cognitive deficits prevalent; however, for the latter to occur, chronic stages could be needed in individuals with obesity." (PMID 38890948, 2024). "In contrast, children with trisomy 21 show elevated leptin levels, reduced resting energy expenditure, and reduced physical activity due to muscular hypotonia and, in addition, hypothyroidism may contribute to obesity." (PMID 39458556, 2024).
Obesity (continued). "The serum concentration of leptin was also shown to be significantly higher in obese asthmatics in comparison to nonobese patients with asthma, while another study showed that there is no independent association between asthma and levels of leptin, adiponectin, or other markers related to obesity." (PMID 38542187, 2024). "Targeted strategies, including the development of leptin sensitizers and lifestyle modifications, may enhance cognitive outcomes while also mitigating the obesity epidemic." (PMID 39594988, 2024). "Notably, leptin, an elevated adipokine in obesity, may play a role in neurogenic inflammation affecting bladder function." (PMID 38172746, 2024). "HCV patients have reduced levels of adiponectin and leptin, and increased levels of resistin, ghrelin and vizfatin, contributing to inflammation, insulin resistance, lipid disorders and atherosclerosis and consequently to the development of hypertension and obesity." (PMID 39457712, 2024). "There are viruses related to the obesity process, known as obesogenic viruses, among which is Adenovirus 36, which increases insulin sensitivity in adipocytes, generating more significant lipogenesis while reducing the expression and secretion of leptin, thus increasing hunger." (PMID 38473918, 2024). "Previous evidence suggests that obesity-induced excessive fat accumulation could trigger the secretion of hormones such as leptin, adiponectin, and adipocytic estrogens, leading to the inhibition of osteoclastogenesis, increased bone formation, and higher bone mineral density." (PMID 39046667, 2024). "In severely burned children, increased adiponectin serum levels correlate with increased leptin serum levels, which is different than the negative correlation between adiponectin and leptin that was reported in healthy individuals, but also in patients with obesity and metabolic syndrome." (PMID 39062875, 2024). "Furthermore, studies indicate that leptin secreted in excess by adipose tissue cells in individuals with obesity affects the hypothalamus–pituitary axis and directly affects cells of the anterior pituitary lobe, thus disrupting the diurnal rhythm of TSH secretion." (PMID 39795885, 2024). "Notably, Lztfl1 knockout mice exhibit hyperphagia, leptin resistance, and obesity." (PMID 39175753, 2024). "Therefore, genes encoding the molecular components of this system might play a role in the development of obesity and related disorders, including leptin, the leptin receptor, POMC, and the melanocortin 4 receptor." (PMID 38391792, 2024). "Obesity is also characterized by increased activity of neprilysin released from adipocytes and kidneys under sympathetic nervous activation, leading to a decrease in natriuretic peptides, which amplifies aldosterone and leptin-dependent renal-pressure natriuresis impairment." (PMID 38186879, 2024). "The metabolic environment as well as the changes that accompany obesity and diabetes are complex, and many hormonal alterations likely contribute to impaired lactation, including systemic and localized elevations of adipokines like leptin, inflammatory cytokines, and insulin." (PMID 37173058, 2023). "However, in many people with obesity, Leptin levels are abnormally high compared to normal levels, and this has been attributed to the development of “leptin resistance”, i.e., impairment of the Leptin signalling pathway." (PMID 37686760, 2023). "Moreover, we hypothesized that adiponectin and leptin hormones explain how obesity and dementia are connected." (PMID 37363537, 2023). "Additionally, obesity might increase central arterial stiffness through leptin, which is a promotor of smooth muscle cell proliferation and angiogenesis." (PMID 37710152, 2023). "Interestingly, while leptin resistance is commonly associated with obesity, not all people with obesity have leptin resistance, and not all people with leptin resistance are obese." (PMID 37600709, 2023).
Obesity (continued). "Exercise and weight loss are associated with a decreased risk of breast cancer recurrence in breast cancer survivors with overweight or obesity, which may be mediated through reduced leptin levels, increased adiponectin levels, and an elevated adiponectin to leptin (A:L) ratio." (PMID 37571390, 2023). "The relatively lower weight loss of setmelanotide-treated BBS patients compared to setmelanotide-treated patients suffering from mutations in the leptin–melanocortin pathway could be explained by the fact that BBS obesity etiology is not entirely known." (PMID 37571382, 2023). "Furthermore, one study, the Kiel Obesity Prevention Study, observed elevated leptin levels in girls with sleep restriction, suggesting that chronic sleep loss may lead to future metabolic alterations." (PMID 38004130, 2023). "Leptin resistance may be induced by a lack of downstream signaling of leptin binding to neuronal receptors as a means of inducing obesity (associated with impaired leptin signaling) or the decreased efficiency of BBB leptin transporters." (PMID 37370490, 2023). "Obesity is a chronic metabolic condition characterized by altered systemic metabolism, including insulin resistance, increased lipid concentrations, abnormal body fat storage, altered adipokine profiles (e.g., increased leptin and decreased adiponectin) and chronic low-grade inflammation." (PMID 37686837, 2023). "However, the exact consequence of leptin signaling on bone tissue in obesity is still unclear." (PMID 36831188, 2023). "Therefore, it could be of great interest to evaluate the effects of Cdc42 inhibitors and activators on leptin resistance and obesity." (PMID 38068822, 2023). "In the case of leptin, several researchers have already suggested that its measurement in serum may be useful in identifying the risk of obesity and/or IR, but there are still no clear definitions of reference values for its level." (PMID 37373485, 2023). "In agreement, Grewal and Buechler demonstrated that adipokines, mainly leptin, resistin and galectin-3, are closely involved in peripheral monocytes and neutrophil responses, which contributes to complications during the course of COVID-19 in patients with obesity." (PMID 37626613, 2023). "What’s more, one of the biological explanations for obesity negatively affects the progression of periodontitis and the response to periodontal therapy may be also due to the unaffected leptin, resistin and adiponectin levels after the periodontal non-surgical treatment." (PMID 37231396, 2023). "Actually, obesity also has a persistent increase in leptin that produces leptin resistance, affects glucose intolerance, and will become a determinant of diabetes, so for this type of obesity, controlling leptin as an intervention target may have the opportunity to prevent various chronic diseases." (PMID 37063322, 2023). "Prior studies have demonstrated the influence of prenatal maternal folic acid intake on offspring’s DNA methylation of IGF2, leptin, and retinoid X receptor-α gene, which have all been shown to be related to growth, energy metabolism, and appetite regulation that affected energy balance and obesity." (PMID 36678251, 2023). "In this context, our data showing down-regulation of PPARG, AP2, LEP and TNFA mRNA levels by Braco-19 treatment of differentiating ASCs suggest that targeting G4 motif might be beneficial against obesity-associated excessive lipid accumulation and inflammation." (PMID 37076894, 2023). "In addition, increased adiponectin and decreased leptin have been observed after a short term high-intensity interval cycling training in young female (mean age 21.7 years) and aged adults (mean age 61 years, 21% male) affected by obesity." (PMID 37608837, 2023). "However, in the context of obesity, resistance to this inflammatory effect of increased energy expenditure may occur mediated by leptin resistance." (PMID 37031749, 2023).